IGKV2D-30 (immunoglobulin kappa variable 2D-30)
Description:
V region of the variable domain of immunoglobulin light chains that participates in the antigen recognition. Immunoglobulins, also known as antibodies, are membrane-bound or secreted glycoproteins produced by B lymphocytes. In the recognition phase of humoral immunity, the membrane-bound immunoglobulins serve as receptors which, upon binding of a specific antigen, trigger the clonal expansion and differentiation of B lymphocytes into immunoglobulins-secreting plasma cells. Secreted immunoglobulins mediate the effector phase of humoral immunity, which results in the elimination of bound antigens. The antigen binding site is formed by the variable domain of one heavy chain, together with that of its associated light chain. Thus, each immunoglobulin has two antigen binding sites with remarkable affinity for a particular antigen. The variable domains are assembled by a process called V-(D)-J rearrangement and can then be subjected to somatic hypermutations which, after exposure to antigen and selection, allow affinity maturation for a particular antigen.
Synonyms: A1; IGKV2D30
Gene: Immunoglobulin variable (V) gene on chromosome 2 (89,936,859 to 89,937,679, forward strand). Ensembl gene ENSG00000239571.
Subcellular location: Secreted; Cell membrane
Pathways (Reactome):
Immune System: Antigen activates B Cell Receptor (BCR) leading to generation of second messengers; CD22 mediated BCR regulation; Classical antibody-mediated complement activation; FCERI mediated Ca+2 mobilization; FCERI mediated MAPK activation; FCERI mediated NF-kB activation; FCGR activation; Fc epsilon receptor (FCERI) signaling; Immunoregulatory interactions between a Lymphoid and a non-Lymphoid cell; Initial triggering of complement; Regulation of Complement cascade; Regulation of actin dynamics for phagocytic cup formation; Role of LAT2/NTAL/LAB on calcium mobilization; Role of phospholipids in phagocytosis
Disease: FCGR3A-mediated IL10 synthesis; FCGR3A-mediated phagocytosis; Potential therapeutics for SARS
Hemostasis: Cell surface interactions at the vascular wall
Vesicle-mediated transport: Scavenging of heme from plasma
Gene Ontology:
Biological process: immune response
Cellular component: extracellular region; immunoglobulin complex; plasma membrane
Homologues: Paralogues in human: IGKV2-30 (99% identical), IGKV2-24 (87% identical), IGKV2D-24 (86% identical), IGKV2D-40 (82% identical), IGKV2-28 (81% identical), IGKV2D-28 (81% identical), IGKV2D-29 (80% identical), IGKV2D-26 (74% identical), IGKV2-40 (68% identical), IGKV3-20 (57% identical), IGKV4-1 (57% identical), IGKV1-39 (56% identical), and 81 more.
Diseases named in the same sentence as IGKV2D-30 in open-access papers:
IGKV2D-30 is named in the same sentence as 2 diseases in open-access papers, as found by Europe PMC text mining. Sharing a sentence is not in itself a finding about the gene and the disease. The quoted sentences say what the papers report.
periodontitis (1 paper, 2025). An acute or chronic inflammatory process that affects the tissues that surround and support the teeth. "These genes have been previously implicated in oxidative stress (GPX2 and GSTA4), immune regulation (CD34 and IGKV2D-30), and RNA processing (NYNRIN), which are all biologically relevant to the inflammatory and immune mechanisms underlying periodontitis." (PMID 41333919, 2025).
systemic lupus erythematosus (1 paper, 2025). An autoimmune multi-organ disease typically associated with vasculopathy and autoantibody production. "The results revealed that the high expression of IGKV2D-30 and CD34 was enriched in pathways, such as chemokine signaling pathway, focal adhesion, systemic lupus erythematosus, et cetera." (PMID 41333919, 2025).